KIF15 (kinesin family member 15)
Description:
Plus-end directed kinesin-like motor enzyme involved in mitotic spindle assembly.
Synonyms: hKLP2; KLP2; KNSL7; NY-BR-62; BRDCS2
Tractability: Small molecule: a structure with a bound ligand is known; a high-quality ligand is known. PROTAC: ubiquitination databases record sites on it; a small molecule that binds it is known.
Target class: Other cytosolic protein
Gene: Protein-coding gene on chromosome 3 (44,761,721 to 44,873,376, forward strand). Ensembl gene ENSG00000163808.
Subcellular location: Cytoplasm; Cytoplasm, cytoskeleton, spindle
Pathways (Reactome):
Hemostasis: Kinesins
Immune System: MHC class II antigen presentation
Vesicle-mediated transport: COPI-dependent Golgi-to-ER retrograde traffic
Gene Ontology:
Molecular function: protein binding; cytoskeletal motor activity; plus-end-directed microtubule motor activity; ATP binding; microtubule binding; microtubule motor activity
Biological process: centrosome separation; mitotic cell cycle; mitotic spindle assembly; microtubule-based movement
Cellular component: membrane; centrosome; cytosol; kinesin complex; plus-end kinesin complex; spindle pole; cytoplasm; spindle
Genetic constraint (gnomAD): Loss-of-function variants: 98 observed, 130.06 expected, observed/expected ratio (o/e) 0.75, 90% interval 0.64 to 0.89. The upper end of that interval is the gene's LOEUF score, 0.89, which puts it in group 3 of 6, group 1 being the genes least tolerant of losing a copy. Missense variants: 1,014 observed, 1,237.1 expected, observed/expected ratio (o/e) 0.82, 90% interval 0.78 to 0.86. Synonymous variants: 413 observed, 451.8 expected, observed/expected ratio (o/e) 0.91, 90% interval 0.84 to 0.99.
Homologues: Orthologues: chimpanzee KIF15 (99% identical), macaque KIF15 (98% identical), pig KIF15 (90% identical), rabbit KIF15 (88% identical), mouse Kif15 (86% identical), rat Kif15 (85% identical), dog KIF15 (79% identical), guinea pig KIF15 (67% identical), tropical clawed frog kif15 (62% identical), zebrafish kif15 (48% identical), Caenorhabditis elegans klp-18 (23% identical), Drosophila melanogaster ncd (10% identical). Paralogues in human: CENPE (21% identical), KIF21A (20% identical), KIF21B (19% identical), KIF4A (19% identical), KIF4B (19% identical), KIF27 (18% identical), KIF7 (18% identical), KIF5A (17% identical), KIF5C (17% identical), KIF13B (17% identical), KIF16B (17% identical), KIF1B (16% identical), and 29 more.
Diseases named in the same sentence as KIF15 in open-access papers:
KIF15 is named in the same sentence as 64 diseases in open-access papers, as found by Europe PMC text mining. Sharing a sentence is not in itself a finding about the gene and the disease. The quoted sentences say what the papers report.
breast carcinoma (24 papers, 2015 to 2026). "A five-gene SLE prognostic signature (RACGAP1, HMMR, TTK, TOP2A, and KIF15) effectively stratified breast cancer survival risk." (PMID 40567613, 2025). "Kif15 has been linked with tumor progression in many cancers, including gastric and breast cancers, by promoting cell proliferation and migration." (PMID 37799807, 2023). "In breast cancer, the differential expression of the KIF15 was associated with prognosis and promoted cell proliferation also through the MEK-ERK pathway." (PMID 33985517, 2021). "We discovered that KIF15 was highly expressed in breast cancer tissues and high level KIF15 was associated with a low survival rate of breast cancer patients." (PMID 32549756, 2020). "A prognostic SLEscore consisting of five SLE-related genes (RACGAP1, HMMR, TTK, TOP2A, and KIF15) could distribute patients with breast cancer into the high- and low-risk groups according to survival rates with good predictive ability (p < 0.05)." (PMID 36726984, 2022). "Previous studies have demonstrated that KIF15 promotes breast cancer progression through its proliferative effects." (PMID 41584727, 2026). "Through TME gene signature analysis, KIF15 was identified as a pivotal driver of the immunosuppressive microenvironment in breast cancer." (PMID 41584727, 2026). "To further investigate the influence of KIF15 on the TME and immunotherapy response in breast cancer, we generated a KIF15‐knockdown murine breast cancer cell line." (PMID 41584727, 2026). "In summary, the immune microenvironment‐derived TMEscore represents an independent prognostic biomarker in breast cancer, while KIF15 emerges as a crucial molecular determinant of its immunosuppressive niche." (PMID 41584727, 2026). "Analysis of multiple breast cancer cohorts from TCGA and GEO consistently revealed elevated KIF15 expression in tumor tissues." (PMID 41584727, 2026). "Kinesins have been recently highlighted as prognostic biomarkers in breast cancer and a 6-KIFs-based risk score (including four MT-Rel genes, KIF4A, KIF15, KIF18B, KIF20A) was reported to accurately predict outcomes." (PMID 37835564, 2023). "KIF15 promotes tumor proliferation and migration in breast cancer, thus resulting in a significantly worse prognosis." (PMID 36726984, 2022). "The novel prognostic SLEscore with five key therapeutic targets (RACGAP1, HMMR, TTK, TOP2A, and KIF15) was developed for the management of breast cancer patients with SLE using the LASSO algorithm." (PMID 36726984, 2022). "KIF15 suppression has been shown to cause cell cycle arrest at the G0/G1 phase in breast cancer cells, indicating that knockdown of KIF15 inhibited the malignant behavior of breast cancer cells." (PMID 35359374, 2022). "Previous studies have shown that KIF15 is overexpressed in a variety of tumors, including pancreatic cancer, lung adenocarcinoma, melanoma, and breast cancer." (PMID 33985517, 2021). "KIF15 is differentially expressed in breast cancer and adjacent tissues, and high levels of KIF15 are significantly correlated with the poor overall survival of patients with breast cancer." (PMID 33011740, 2020). "To further analysis the relationship between the expression of KIF15 and clinical-pathological characteristics of breast cancer, we defined weak and moderate staining as normal-expression and strong staining as over-expression." (PMID 32549756, 2020). "What's more, western blot and immunohistochemistry assay were utilized to evaluate the protein level and mRNA level of KIF15 in breast cancer tissues." (PMID 32549756, 2020). "Elevated expression levels of kinesins KIF14, KIF4A, KIF20A, and KIF23, KIF2C, and KIFC1 have been reported in breast cancer cell lines, other kinesins KIF10, KIF18A, and KIF15 have been linked to prognostic indicators in breast cancer patients." (PMID 32346924, 2020).
breast carcinoma (continued). "In short, ZNF367-activated KIF15 accelerated the progression of breast cancer by regulating cell cycle progress." (PMID 32549756, 2020). "Overexpression of KIF15 in breast cancer was significantly correlated with higher WHO grade (P<0.0001) and higher Ki-67 level (P=0.002)." (PMID 32549756, 2020). "We tested the expression of KIF15 in breast cancer tissues and the survival rate of breast cancer patients with high or low level of KIF15 through TCGA data." (PMID 32549756, 2020). "Recent study has reported that knockdown of KIF15 effectively promoted the apoptosis in breast cancer cells." (PMID 32322172, 2020). "On the whole, this study uncovered that ZNF367-activated KIF15 accelerated the progression of breast cancer and exerted the vital functions on cell cycle." (PMID 32549756, 2020). "Overall, ZNF367 positively regulated KIF15 through transcriptionally activating KIF15 in breast cancer." (PMID 32549756, 2020). "Taken together, ZNF367 transcriptionally activated KIF15 and accelerated the progression of breast cancer." (PMID 32549756, 2020). "KIF15 supports K5I resistance in HeLa cells, which is shown to act as target for endocrine therapy-resistant breast cancer." (PMID 31708970, 2019). "KIF15 is the breast cancer tumor antigen and is necessary for the maintenance of spindle bipolarity." (PMID 31708970, 2019). "Moreover, we discovered that KIF15 acts as a pivotal regulator of immunosuppression in breast cancer." (PMID 41584727, 2026). "Separately, we identified KIF15 as a potential driver of immunosuppression in breast cancer." (PMID 41584727, 2026). "Six variants had no additional breast-cancer-affected carriers identified in the pedigrees they were originally found in (in genes KIF15, TMEM192, MUC5AC, TEP1, ZFX, and TNN)." (PMID 38136396, 2023). "In addition, KIF15 is being considered as a prognostic marker and a new endocrine therapy target for breast cancer." (PMID 33985517, 2021). "Moreover, it has been demonstrated that KIF15 plays an important role in the development of several types of human cancers such as pancreatic cancer, lung adenocarcinoma and breast cancer." (PMID 33985517, 2021). "In short, these results demonstrated that ZNF367 and KIF15 could regulate cell cycle in breast cancer." (PMID 32549756, 2020). "Recently, KIF15 was reported to be overexpressed in several types of human diseases such as glioma and breast cancer, and may facilitate these diseases." (PMID 32322172, 2020). "In our research, we investigated the function of KIF15 in breast cancer." (PMID 32549756, 2020). "And rescue experiments indicated that overexpressed KIF15 could counteract the inhibition effect of silencing ZNF367 on the progression of breast cancer." (PMID 32549756, 2020). "It was indicated that ZNF367 and KIF15 could regulate cell cycle in breast cancer so as to accelerate the progression of breast cancer." (PMID 32549756, 2020). "The purpose of our research was to investigate the functions of KIF15 in breast cancer." (PMID 32549756, 2020). "KIF15 was expressed in cytoplasm and occasionally at nucleus in breast cancer cells." (PMID 32549756, 2020). "Therefore, we hypothesized that KIF15 could mediate the immunosuppressive TME in breast cancer by inhibiting dendritic cell infiltration." (PMID 41584727, 2026). "Moreover, KIF15 was reported to be notably upregulated in several cancer tissues compared with adjacent tissues such as breast cancer and glioma, implying that KIF15 could serve as a potential prognostic biomarker and therapeutic target." (PMID 36837615, 2023). "Moreover, ZNF367 could induce the transcriptional activation of kinesin family member 15, leading to elevated cell viability and invasion ability in breast cancer cells." (PMID 35768832, 2022).
breast carcinoma (continued). "have found that the upregulation of KIF15 in breast cancer tissues was positively related to TNM stage, tumor size, and lymph node metastasis; while downregulation of KIF15 inhibited cell proliferation and tumor proliferation in vitro and in vivo." (PMID 35359374, 2022). "Ectopic expression of KIF20A promoted chemoresistance of CRC cells to oxaliplatin or 5-FU treatment by decreasing apoptosis 37 and also indicated that expression of KIF4A, KIF15, KIF20A and KIF23 was correlated with prognosis in breast cancer." (PMID 33995648, 2021). "As already shown in breast cancer, we also find several members of the Kinesin protein family (KIF11, KIF15, KIF23, KIF2C and KIFC1) to be upregulated in patients with high expression of ATAD2." (PMID 26308378, 2015). "Additionally, study found that 26 of 38 kinesins detected in breast cancer MCF-7 cells are regulated by estrogen 17β-estradiol (E2) and many of them are upregulated by E2, including KIF15, KIF4A, KIF20A, and KIF23." (PMID 31729978, 2019). "Hklp2/KIF15, another Ki-67 interacting protein, plays a critical role in the maintenance of spindle bipolarity during cell division and was reported to serve as a breast cancer tumor antigen." (PMID 26984280, 2016).
pancreatic cancer (12 papers, 2019 to 2025). "For instance, aberrant KIF15 expression promotes pancreatic cancer growth by activating the MEK/ERK signaling pathway." (PMID 40087774, 2025). "The exploration of KIF15-mediated endosome trafficking of integrin β1 will help uncover the related pancreatic cancer distant metastasis mechanisms." (PMID 36280663, 2022). "have also shown that KIF15 promoted pancreatic cancer growth by enhancing G1/S phase transition by affecting the MEK–ERK signalling pathway." (PMID 35359374, 2022). "In pancreatic cancer, KIF15 promotes the proliferation of cancer cells through the MEK-ERK signaling pathway." (PMID 33985517, 2021). "Recently, KIF15 has been reported to be highly expressed in gastrointestinal (GI) track cancers such as pancreatic cancer and hepatocellular cancer." (PMID 32322172, 2020). "A previous study indicated that KIF15 promotes pancreatic cancer proliferation via the MEK-ERK signaling pathway." (PMID 33011740, 2020). "Moreover, KIF15 has been reported to promote development of digestive tumors such as pancreatic cancer." (PMID 32322172, 2020). "It was reported that KIF15 could promote pancreatic cancer cell proliferation as a tumor promoting factor." (PMID 32322172, 2020). "Genes, such as CDCA3, KIF15, and TCF19, are linked with the proliferation of various cancer cells, such as oral cancer, pancreatic cancer, and hepatocellular carcinoma cells, but these genes may be responsible for the proliferation of BRCA cells." (PMID 31311202, 2019). "KIF15 is responsible for USP10-induced PGK1 deubiquitination, thereby enhancing the glycolytic capacity for pancreatic tumor growth." (PMID 40087774, 2025). "Previous studies have reported the overexpression of KIF11, KIF15, and KIF18B in various malignancies, including gallbladder cancer, oral cancer, meningioma, pancreatic cancer, and osteosarcoma, supporting our findings." (PMID 37711200, 2023). "Over-expression of KIF15 increases the cyclin-D1, CDK2, p-RB expression, and accelerated G1/S transition in pancreatic cancer cells." (PMID 35359374, 2022). "Therefore, we conclude that due to the acetylation modification of SIRT1 on KIF15, the integrin β1/FAK pathway of KIF15-overexpressed pancreatic cancer cell was activated, providing a prerequisite for the metastasis inhibition effect of EX527 combined with KIF15-IN-1." (PMID 36280663, 2022). "Moreover, Zhao’s group identified KIF15 as a upstream regulator of MEK-ERK signaling pathway, by which may KIF15 promoted pancreatic cancer." (PMID 32439830, 2020).
hepatocellular carcinoma (10 papers, 2013 to 2026). A malignant tumor that arises from hepatocytes. "Recently, KIF15 has been proven to be over-expressed in various cancers including gastric cancer, hepatocellular carcinoma, and lung adenocarcinoma." (PMID 35359374, 2022). "For example, KIF15 can promote cancer stem cell phenotype in hepatocellular carcinoma, while KIF18B can promote cell proliferation in hepatocellular carcinoma." (PMID 35524313, 2022). "Kif15 has been previously reported to be widely involved in the progression of several malignancies, such as hepatocellular carcinoma (HCC), and gastric, breast, colorectal, and prostate cancer by regulating cell cycle, migration, and invasion." (PMID 35370541, 2022). "In hepatocellular carcinoma, ATAD2 modulates the expression of kinesin family member 15, which interacts with phosphoglycerate dehydrogenase to prevent its proteasomal degradation." (PMID 41158756, 2026). "Kinesin family member 15 (KIF15) promotes the CSC phenotype and malignancy by means of PHGDH-mediated ROS imbalance in hepatocellular carcinoma." (PMID 36213825, 2022).
prostate carcinoma (8 papers, 2020 to 2025). A carcinoma that arises from epithelial cells of the prostate gland. "KIF15 was up-regulated in prostate cancer (PCa), and its higher level was associated with poorer clinical outcomes." (PMID 40087774, 2025). "Except for the loss-of-function assays, the function of KIF15 in prostate cancer was further verified through gain-of-function assays." (PMID 37658042, 2023). "KIF15 is highly expressed in prostate cancer tissues and is associated with poor prognosis." (PMID 37658042, 2023). "The loss-of-function and gain-of-function assays based on prostate cancer cells indicated that the change in KIF15 expression could significantly affect cell proliferation, tumorigenesis, migration, and cell apoptosis." (PMID 37658042, 2023). "In this study, we found that down-regulation of KIF15 inhibited the proliferation, tumorigenesis, and migration of prostate cancer cells, as well as the subcutaneous tumor formation of prostate cancer cells through the PI3K/Akt pathway." (PMID 37658042, 2023). "The purpose of the study was to explore the significance and role of KIF15 in prostate cancer and to show some potential value for prostate cancer." (PMID 37658042, 2023). "Subsequently, the examination of prostate cancer cell phenotypes revealed completely opposite effects of KIF15 overexpression compared with KIF15 knockdown." (PMID 37658042, 2023). "Correspondingly, overexpression of KIF15 in prostate cancer cells executed completely opposite regulatory effects." (PMID 37658042, 2023). "Immunohistochemistry analysis showed that KIF15 was highly expressed in prostate cancer tissues, which was also positively correlated with T Infiltrate." (PMID 37658042, 2023). "The results showed that KIF15 expression was relatively higher in prostate cancer cells than in normal cells." (PMID 37658042, 2023). "In this study, we found a high expression of KIF15 in prostate cancer and demonstrated that the expression of KIF15 was positively correlated with T Infiltrate, which suggested the potential correlation between KIF15 and prostate cancer development." (PMID 37658042, 2023). "All these results provided evidence of the involvement of KIF15 in the development of prostate cancer." (PMID 37658042, 2023). "CCK8 assay, flow cytometry, colony formation assay, and Transwell assay were used to evaluate the effects of down-regulation of KIF15 on prostate cancer phenotypes in vitro." (PMID 37658042, 2023). "First of all, the expression of KIF15 was detected in 155 cases of prostate cancer tissue and 79 cases of normal prostate tissue." (PMID 37658042, 2023). "In summary, KIF15 was identified to play an important role in the development or biological progress of prostate cancer and is considered to possess the potential to be used as a therapeutic target." (PMID 37658042, 2023). "The upregulation of KIF15 in prostate cancer cells accelerated cell proliferation, enhanced the formation of colonies, inhibited cell apoptosis, and promoted cell migration." (PMID 37658042, 2023). "Statistical analysis showed that the expression of KIF15 in prostate cancer tissues was significantly higher than that in normal prostate tissues (P < 0.001)." (PMID 37658042, 2023). "In vitro experiments showed that KIF15 had significant effects on the phenotypes of prostate cancer cells." (PMID 37658042, 2023). "Recent studies reported that an increased expression of KIF4A and KIF15 are potential prognostic factors in prostate cancer and lung adenocarcinoma, respectively." (PMID 32703154, 2020). "Collectively, the involvement of KIF15 in prostate cancer development was further proved." (PMID 37658042, 2023). "Bearing all these in mind, our research group speculated that KIF15 may play an important role in the development and progression of prostate cancer." (PMID 37658042, 2023).